RBMS1 (RNA binding motif single stranded interacting protein 1)
Description:
Single-stranded DNA binding protein that interacts with the region upstream of the MYC gene. Binds specifically to the DNA sequence motif 5'-[AT]CT[AT][AT]T-3'. Probably has a role in DNA replication.
Synonyms: C2orf12; MSSP; SCR2; MSSP-1; MSSP-2; MSSP-3; YC1; HCC-4; DKFZp564H0764
Tractability: PROTAC: ubiquitination databases record sites on it.
Gene: Protein-coding gene on chromosome 2 (160,272,151 to 160,494,100, reverse strand). Ensembl gene ENSG00000153250.
Subcellular location: Nucleus
Subcellular location (Human Protein Atlas): Cytosol
Gene Ontology:
Molecular function: protein binding; RNA binding; double-stranded DNA binding; mRNA 3'-UTR binding; poly(U) RNA binding; single-stranded DNA binding; nucleic acid binding
Biological process: DNA replication; RNA processing
Cellular component: cytosol; nucleus; ribonucleoprotein complex
Genetic constraint (gnomAD): Loss-of-function variants: 13 observed, 50.29 expected, observed/expected ratio (o/e) 0.26, 90% interval 0.17 to 0.41. The upper end of that interval is the gene's LOEUF score, 0.41, which puts it in group 1 of 6, group 1 being the genes least tolerant of losing a copy. Missense variants: 304 observed, 471.95 expected, observed/expected ratio (o/e) 0.64, 90% interval 0.59 to 0.71. Synonymous variants: 157 observed, 159.97 expected, observed/expected ratio (o/e) 0.98, 90% interval 0.86 to 1.12.
Homologues: Orthologues: chimpanzee RBMS1 (100% identical), dog RBMS1 (99% identical), rat Rbms1 (96% identical), mouse Rbms1 (96% identical), guinea pig RBMS1 (94% identical), macaque RBMS1 (94% identical), pig RBMS1 (93% identical), rabbit RBMS1 (92% identical), tropical clawed frog rbms1 (86% identical), zebrafish rbms1a (69% identical). Paralogues in human: RBMS3 (73% identical), RBMS2 (67% identical), PABPC1 (28% identical), PABPC1L (27% identical), PABPC3 (26% identical), ELAVL2 (26% identical), PABPC4 (25% identical), ELAVL4 (25% identical), PUF60 (24% identical), ELAVL3 (23% identical), HNRNPR (22% identical), SYNCRIP (22% identical), and 12 more.
Diseases named in the same sentence as RBMS1 in open-access papers:
RBMS1 is named in the same sentence as 60 diseases in open-access papers, as found by Europe PMC text mining. Sharing a sentence is not in itself a finding about the gene and the disease. The quoted sentences say what the papers report.
lung carcinoma (20 papers, 2019 to 2025). "Taken together, our data suggest that high RBMS1 expression is associated with lung cancer metastasis." (PMID 38342601, 2024). "Particularly in lung cancer, the protein RBMS1 has been implicated in radioresistance by modulating the expression of SLC7A11." (PMID 38515565, 2024). "Collectively, these results indicate that RBMS1 deficiency inhibits lung cancer metastasis in vitro and in vivo." (PMID 38342601, 2024). "Here it is reported that the RNA‐binding protein RBMS1 is positively associated with increased lymph node metastasis in non‐small cell lung cancer (NSCLC)." (PMID 38342601, 2024). "In addition, elevated RBMS1 was observed in lung cancer patients, and RBMS1 deficiency inhibited the translation of SLC7A11 and promoted ferroptosis through the translation initiation factor eIF3d." (PMID 41214391, 2025). "Recent investigations have unveiled that N-desmethyl imipramine hydrochloride (NTP) can alter RBMS1 expression in IR-resistant A549 lung cancer cells, thereby enhancing their susceptibility to radiation therapy, which opens a new therapeutic avenue for lung cancer treatment." (PMID 38515565, 2024). "In lung cancer, the RNA-binding protein RBMS1 augmenting the expression of SLC7A11 leads to an elevation in the production of GSH and consequently suppresses ferroptosis." (PMID 40765833, 2025). "Previous studies have shown that nortriptyline participated in the progression of lung cancer by inhibiting RBMS1 expression." (PMID 41214391, 2025). "Intriguingly, we found that NTP treatment reduced the levels of RBMS1 and S100P in both A549 and H460 lung cancer cells in a dose‐dependent manner." (PMID 38342601, 2024). "Most importantly, lung cancer patients with high expression of RBMS1 and S100P had a worse prognosis than those with low expression of RBMS1 and S100P." (PMID 38342601, 2024). "Taken together, our study revealed that RBMS1 is a promising anti‐metastasis target and the RBMS1 inhibitor NTP is a potent therapeutic agent for anti‐metastasis therapy in human lung cancer." (PMID 38342601, 2024). "The RNA-binding protein RBMS1 plays a role in lung cancer development by facilitating the evasion of ferroptosis, making it a crucial regulator of this process." (PMID 38962561, 2024). "To investigate the potential effect of RBMS1 on lung cancer metastasis, we stably depleted RBMS1 in A549, H460 and H2170 lung cancer cells using two short‐hairpin RNAs (shRNAs)." (PMID 38342601, 2024). "We established a mouse lung cancer metastasis model by injecting the mouse tail vein with A549 cells stably depleted RBMS1 or control." (PMID 38342601, 2024). "To confirm these findings, we further examined the effect of RBMS1 knockdown on lung cancer metastasis in vivo." (PMID 38342601, 2024). "To investigate the clinical relevance of RBMS1 and S100P in lung cancer, we examined the protein levels of RBMS1 and S100P in fresh‐frozen tumor and paired adjacent normal tissues from 7 patients with NSCLC." (PMID 38342601, 2024). "Altogether, our data indicate that RBMS1 is a promising anti‐metastasis target, and the RBMS1 inhibitor NTP is a potent therapeutic agent for anti‐metastasis therapy in human lung cancer." (PMID 38342601, 2024). "A study investigated the role of RBMS1 in regulating ferroptosis in lung cancer through translational control of SLC7A11." (PMID 38383297, 2024). "Compound NTP, as RBMS1 inhibitor, has shown promising efficacy in the treatment of lung cancer cells and in mouse models of tumor metastasis." (PMID 38342601, 2024). "Collectively, our clinical data reveal that RBMS1 is positively correlated with S100P in lung cancer patient samples." (PMID 38342601, 2024). "Given that RBMS1 affected cell growth by ferroptosis-dependent manner in lung cancer, we evaluated the effect of RBMS1 on ferroptosis of HCC cells." (PMID 36989117, 2023).
lung carcinoma (continued). "More importantly, RBMS1 is also identified to modulate the evasion of ferroptosis during lung cancer progression through interacting with the translation initiation factor eIF3d directly to bridge the 3’- and 5’ UTR of SLC7A11." (PMID 36989117, 2023). "RBMS1 depletion or inhibition of RBMS1 expression by nortriptyline hydrochloride sensitizes radioresistant lung cancer cells to radiotherapy through promoting ferroptosis." (PMID 37714846, 2023). "Recent studies have shown that increased RBMS1 in lung cancer is proportional to survival in patients." (PMID 36989117, 2023). "In the case of lung cancer cells, RBMS1 inhibits SLC7A11 expression, thereby reducing SLC7A11-mediated cystine uptake and facilitating ferroptosis in lung cancer cells." (PMID 37728413, 2023). "Meanwhile, our recent study revealed that RBMS1 regulates lung cancer ferroptosis through translational control of SLC7A11." (PMID 35538152, 2022). "Moreover, RBMS1 (RNA binding motif single-stranded interacting protein 1) expression was significantly elevated in lung cancer and is closely related to tumor metastasis." (PMID 39875356, 2025). "For example, RBMS1 regulated lung cancer ferroptosis through translational control of SLC7A11." (PMID 38605214, 2024). "Targeting RBMS1 has the potential to be an effective treatment strategy for lung cancer patients." (PMID 38342601, 2024). "Meanwhile, RBMS1 was stably overexpressed in both A549 and H460 lung cancer cells." (PMID 38342601, 2024). "For lung cancer, RNA-binding protein RBMS1-mediated ferroptosis evasion promoted its development." (PMID 36163032, 2022). "Depletion of RBMS1 sensitizes ionizing radiation (IR) resistant lung cancer cells to ferroptosis." (PMID 35882850, 2022). "In addition, RBMS1, directly interacting with translation initiation factor eIF3d, promotes lung cancer progression through translational regulating SLC7A11." (PMID 35882850, 2022). "Likewise, a similar relationship was observed between RNA binding protein RBMS1 and SLC7A11, in a way that depletion of RBMS1 sensitizes lung cancer cells to ferroptosis and radiotherapy." (PMID 34926310, 2021). "Moreover, our findings that RBMS1 expression positively correlates with lung cancer metastatic progression and RBMS1 knockdown attenuates tumor metastasis, suggest that RBMS1 may represent an attractive anti‐metastatic target for lung cancer treatment." (PMID 38342601, 2024). "Moreover, posttranslational regulation of SLC7A11 by RBMS1 mediates ferroptosis in lung cancer." (PMID 37210575, 2023). "Previous studies demonstrated that the RBP RBMS1 binds to SLC7A11 mRNA to enhance its translation, contributing to ferroptosis resistance in lung cancer." (PMID 40695795, 2025). "This interaction leads to the regulation of SLC7A11 expression by RBMS1 through EIF3D, consequently inhibiting ferroptosis and promoting the progression of lung cancer." (PMID 38654320, 2024). "Research indicates that RBMS1, as a translation regulator for ferroptosis, promotes the translation of SLC7A11 through its T3 region in the 3′-UTR, leading to an escape from ferroptosis and furthering lung cancer progression." (PMID 38515565, 2024). "RNA‐binding motif, single‐stranded‐interacting protein 1 (RBMS1) is a promising anti‐metastatic target and the RBMS1 inhibitor nortriptyline hydrochloride (NTP) is a potent therapeutic agent for anti‐metastatic therapy in human lung cancer." (PMID 38342601, 2024). "Knocking down RBMS1 suppressed the translation of SLC7A11 and reduced SLC7A11C-mediated cystine uptake and eventually facilitated ferroptosis and sensitized radioresistant lung cancer cells to radiotherapy." (PMID 36989117, 2023). "Importantly, we found that higher RBMS1 expression level was significantly correlated with clinical stage (P = 0.0491) and lymph node metastasis (P = 0.028) in lung cancer patients, but not with other factors, including sex, age, and tumor size." (PMID 38342601, 2024).
lung carcinoma (continued). "Interestingly, the mRNA level of S100P was not affected by RBMS1 in both the stably RBMS1‐depleted lung cancer cells and in those with RBMS1 transient knock‐down using siRNA, indicating that RBMS1 might regulate the expression of S100P at the post‐RNA level, including translation." (PMID 38342601, 2024).
colon cancer (8 papers, 2021 to 2025). "RBMS1 was identified as suppressor of colon cancer progression, and downregulation was negatively associated with patients’ survival." (PMID 40489530, 2025). "RBMS1 has been previously reported to inhibit colon cancer metastasis with clinical utility for risk stratification of patients." (PMID 35538152, 2022). "Concurrently, the RBMS1/PRNP axis enhances oxaliplatin resistance in colon cancer, thereby contributing to ferroptosis resistance." (PMID 41394830, 2025). "Our results reveled that the role of RBMS1 in NSCLS metastasis is different from that in colon cancer." (PMID 38342601, 2024). "As a post-transcriptional regulator of RNA stability, RBMS1 has clear significance for the progression of colon cancer." (PMID 34804951, 2021). "In a mouse model of xenotransplantation, silencing RBMS1 increased the metastatic ability of colon cancer cells while restoring RBMS1 weakened the metastatic capacity of colon cancer cells." (PMID 34804951, 2021). "Furthermore, miR-4442 regulated EMT through RBMS1, a suppressor of mesenchymal characteristics in colon cancer cells." (PMID 37510319, 2023). "As RBMS1 was previously reported to be a suppressor of epithelial-mesenchymal transition (EMT) and metastatic liver colonization in colon cancer cells, we further detected EMT-associated marker expression levels after overexpression and knockdown of RBMS1 in both SGC-7901 and HGC-27 cell lines." (PMID 35361764, 2022). "Further investigation revealed a significant correlation between the expression of RBMS1 and RBMS3 and the clinical stage of colon cancer." (PMID 38618967, 2024). "Our results unveiled a noteworthy reduction in the expression of RBMS1 and RBMS3 in colon cancer in comparison to normal colon tissues." (PMID 38618967, 2024). "These discoveries indicate the potential pivotal role of RBMS1 and RBMS3 in the context of colon cancer." (PMID 38618967, 2024). "Furthermore, we examined the expression of RBMS1 and RBMS3 in normal colon tissues and colon cancer using Western blot and qRT‐PCR." (PMID 38618967, 2024).
breast carcinoma (6 papers, 2013 to 2025). "It has been shown that loss of RBMS1 enhances anti-tumor immunity in breast cancer by blocking PD-L1 checkpoints." (PMID 41214391, 2025). "Here, we also observed a strong correlation between RBMS1 and PD-L1, not only in breast cancer, but also in multiple cancers." (PMID 37628671, 2023). "We further re-expressed B4GALT1 in RBMS1-depleted breast cancer cells, and found that re-expression of B4GALT1 rescued RBMS1 depletion-induced decrease of PD-L1 glycosylation." (PMID 35538152, 2022). "We observed that RBMS1 is highly expressed in breast cancer samples, especially in TNBC samples, which is positively correlated to PD-L1 level." (PMID 35538152, 2022). "Clinically, RBMS1 was increased in breast cancer and its level was positively correlated to that of PD-L1." (PMID 35538152, 2022). "We found that the glycosyltransferase beta-1,4-galactosyltransferase 1 (B4GALT1) was one of the top hits whose expression level was significantly decreased upon RBMS1 depletion in breast cancer cells." (PMID 35538152, 2022). "To investigate the potential clinical association between RBMS1 and PD-L1, we measured the protein levels of RBMS1 and PD-L1 on human breast cancer tissue microarrays containing 50 breast cancer patient samples by immunohistochemistry (IHC) assay." (PMID 35538152, 2022). "On the basis of unbiased bioinformatic analyses of RBPs in breast cancers with distinct immune status, we identified RBMS1 to be accumulated in TNBC tumors." (PMID 35538152, 2022). "Further analysis showed that RBMS1 is the top increased RBP in basal vs other subtypes of breast cancer among the RNA binding proteins analyzed." (PMID 35538152, 2022). "Meanwhile, depletion of B4GALT1 in breast cancer cells with overexpression of RBMS1 notably reduced the glycosylation of PD-L1." (PMID 35538152, 2022). "Conversely, overexpression of RBMS1 elevated the level of PD-L1 in multiple breast cancer cells." (PMID 35538152, 2022). "Potential oncogenes amplified in the breast cancer include GREB1, NRXN1, MGAT5, PKP4, DAPL1, ITGB6, and RBMS1, which may be implicated in carcinogenesis, proliferation, and invasion." (PMID 26432421, 2015). "However, the expression and function of RBMS1 in breast cancer is less understood." (PMID 35538152, 2022). "In addition, our clinical observations demonstrated that RBMS1 is positively correlated to PD-L1 in breast cancer samples, suggesting that RBMS1 might be involved in regulating PD-L1 expression in breast cancer, especially TNBC." (PMID 35538152, 2022). "We subsequently analyzed the clinical correlation of RBMS1 and B4GALT1 in TCGA breast cancer dataset, and found that the expression level of B4GALT1 is positively correlated to the level of RBMS1, especially in TNBC dataset." (PMID 35538152, 2022). "RBMS1 directly stabilizes the mRNA of B4GALT1, a glycosyltransferase that promotes PD-L1 maturation and stabilization via mediating the glycosylation of PD-L1 in breast cancer." (PMID 37628671, 2023). "RBMS1 ablation significantly reduced PD-L1 level, thus to stimulate CD8+ CTL population and Granzyme B release and enhance the T-cell-mediated cancer cell killing, suggesting that RBMS1 plays an important role in breast cancer immunotherapy regulation." (PMID 35538152, 2022). "We showed that >60% of breast cancer samples exhibited strong or extra-strong staining for both of RBMS1 and PD-L1, whereas most of the normal breast tissues (~80%) displayed weak positive/negative staining for RBMS1 and PD-L1." (PMID 35538152, 2022). "Moreover, in a panel of breast cancer cell lines, the level of RBMS1 was notably elevated in TNBC cells (e.g. MDA-MB-231 and HCC1937) as compared to normal breast cells and other subtype breast cancer cells, indicating that RBMS1 might regulate the PD-L1 checkpoint immune surveillance in TNBC." (PMID 35538152, 2022).
gastric cancer (6 papers, 2022 to 2025). A primary or metastatic malignant neoplasm involving the stomach. "In gastric cancer cells, single stranded interacting protein 1 (RBMS1) was discovered to activate the JAK2/STAT3 downstream signaling pathway after binding to the transcription factor MYC, subsequently increasing cancer migration and invasion." (PMID 38182570, 2024). "Finally, we expect to further validate the role of KCNQ1OT1/miR-378a-3p/RBMS1 axis in gastric cancer in the next study owing to the current experimental constraints." (PMID 35910231, 2022). "A recent study demonstrated that the RBMS1 locus acts by regulating the expression of the miR-106b, which has been found overexpressed in hepatocellular carcinoma, cervical cancer, renal carcinoma, and gastric cancer." (PMID 35625981, 2022). "Overexpression of RBMS1 in HGC-27 and SGC-7901 cells increased the migration and invasion of gastric cancer cells by binding to the transcription factor MYC and activating the IL-6/JAK2/STAT3 signaling pathway." (PMID 41214391, 2025). "However, there are still no studies on how the KCNQ1OT1, miR-378a-3p, and RBMS1 axis play a role in the development and progression of gastric cancer." (PMID 35910231, 2022).
Obesity (5 papers, 2015 to 2026). Accumulation of substantial excess body fat. "Multiple studies have found that single nucleotide polymorphisms (SNPs) in RBMS1 are linked to the risk of type 2 diabetes mellitus and other obesity-related traits." (PMID 37511060, 2023). "RBMS1 polymorphism has been shown to be associated with obesity and type 2 diabetes, but the role of RBMS1 in adipose metabolism and adipogenesis is not known." (PMID 37511060, 2023). "Furthermore, exploring the role of RBMS1 in human adipose tissue and assessing whether genetic variants or altered expression patterns correlate with obesity, insulin resistance, or type 2 diabetes could clarify its clinical significance." (PMID 41596407, 2026). "The variant rs1829975, intergenic in RBMS1-TANK, a region that has been associated with several obesity related traits, reached the genome-wide significance threshold (Pdiff < 5*10-8) in the men lean-overweight contrast." (PMID 25811787, 2015). "They include the locus RBMS1-TANK (men, Pdifflean-overweight= 4.7 x 10-8), a region that has been associated with several obesity related traits, and TSPYL5 (men, Pdifflean-overweight= 9.1 x 10-8), regulating adipocytes-produced estradiol." (PMID 25811787, 2015). "Given ATGL’s central role in lipolysis, disruption of its regulation by RBMS1 could contribute to metabolic pathologies including obesity and diabetes." (PMID 41596407, 2026). "Our findings imply that RBMS1 plays an important role in adipocyte metabolism and may offer novel therapeutic opportunity for metabolic disorders such as obesity and type 2 diabetes." (PMID 37511060, 2023). "We show that RBMS1 may play an important role in the regulation of adipocyte differentiation and metabolism and may offer a novel therapeutic opportunity for metabolic disorders such as obesity and type 2 diabetes." (PMID 37511060, 2023).
type 2 diabetes (5 papers, 2015 to 2026). "Moreover, genetic studies have identified RBMS1 polymorphisms as risk factors for type 2 diabetes, underscoring its role in metabolic regulation." (PMID 41596407, 2026). "In addition, RBMS1 polymorphism has been found to be significantly associated with an increased risk of developing type 2 diabetes in several populations, suggesting a possible role in metabolic regulation as well." (PMID 37511060, 2023).